ELAVL1 (ELAV like RNA binding protein 1)
Diseases named in the same sentence as ELAVL1 in open-access papers (continued):
Sharing a sentence is not in itself a finding about the gene and the disease.
amyotrophic lateral sclerosis (8 papers, 2018 to 2025). Amyotrophic lateral sclerosis (ALS) is a neurodegenerative disease characterized by progressive muscular paralysis reflecting degeneration of motor neurons in the primary motor cortex, corticospinal tracts, brainstem and spinal cord. "Elavl1 is implicated in the activation of astrocytes and microglia, and is particularly overexpressed in the spinal cord microglia of humans and mice with amyotrophic lateral sclerosis (ALS)." (PMID 40000387, 2025). "On the other hand, ELAVL1 has been found to play deleterious roles in Huntington’s disease and amyotrophic lateral sclerosis." (PMID 35465324, 2022). "Moreover, inhibition of ELAVL1 has been shown to block the chronic activation of microglia in amyotrophic lateral sclerosis and to delay the course of this disease." (PMID 35465324, 2022). "Silencing ELAVL1/HuR, which also shares high amino acid identity with FNE in the activated microglia and astrocytes attenuate neuroinflammation and the occurrence of amyotrophic lateral sclerosis." (PMID 36438188, 2022).
COVID-19 (8 papers, 2021 to 2025). A disease caused by infection with severe acute respiratory syndrome coronavirus 2. "The analysis of ELAVL1 expression in distinct respiratory cell populations among individuals with COVID-19 and COPD unveiled a noteworthy positive correlation between ELAVL1 and ACE2, particularly in cells affected by COPD." (PMID 38601162, 2024). "RNA export adapter proteins such as LRPPRC or ELAVL1 also function as readers of RNA N6-methyladenosine modification (m6A), which is crucial for the transmission and pathogenicity of COVID-19." (PMID 38674024, 2024). "We analyzed scRNA-seq data to profile ELAVL1 expression in distinct respiratory cell populations in COVID-19 and COPD patients." (PMID 35011584, 2021). "We observed that RBM15B, HNRNPA2B1, and VIRMA may be protective factors in the development of COVID-19, and the opposite performance was found in ELAVL1, RBM15, FMR1, IGFBP3, and METTL3." (PMID 35655464, 2022). "We also sought to comprehensively profile the expression of HuR/ELAVL1 in the various cells of lungs from COPD and COVID-19 patients." (PMID 35011584, 2021). "Using scRNA-seq datasets, we first profiled the differential expression of ELAVL1 in cells of the upper and lower respiratory system in COPD and COVID-19 subjects." (PMID 35011584, 2021). "Similarly, the specific role of VIRMA, ELAVL1, and FMR1 in COVID-19 was mentioned in several studies." (PMID 35655464, 2022). "It is also not known whether HuR/ELAVL1 expression changes in the context of lung disease, including COVID-19 and COPD, or whether the upregulation of ACE2 in smokers and COPD is regulated by HuR." (PMID 35011584, 2021).
diabetic retinopathy (6 papers, 2018 to 2025). "Elavl1 also plays a role in diabetic retinopathy by stabilizing mRNAs of TNF-α and VEGF, promoting disease progression." (PMID 40000387, 2025). "Inhibiting Elavl1 expression has shown promise in slowing diabetic retinopathy, making it a potential therapeutic target for retinal diseases." (PMID 40000387, 2025). "miR-192-5p is involved in diabetic retinopathy, as its upregulation inhibits the ELAVL1/PI3Kδ axis and attenuates microvascular endothelial cell proliferation, migration, and angiogenesis." (PMID 41295241, 2025).
esophageal cancer (6 papers, 2020 to 2025). A primary or metastatic malignant neoplasm involving the esophagus. "Here, for the first time, we had used siRNA fragments to provide a mechanism that linked ELAVL1 with phospholipid remodeling, proving ELAVL1 was involved in the overexpression of LPCAT2, which further catalyzed the conversion of LPC (16:0) to PC (16:0/18:1) in esophageal cancer cells." (PMID 32733803, 2020). "The in vitro results showed that angustoline activated the expressions of LKB1 and AMPK and subsequently inhibited the levels of ELAVL1 and LPCAT2, which elucidated the anti-tumor mechanism of angustoline in esophageal cancer cell model." (PMID 32733803, 2020). "Additionally, the effects of angustoline on viability, migration and invasion of esophageal cancer cells (KYSE450) were evaluated, as well as the regulation of angustoline in LKB1/AMPK/ELAVL1/LPCAT2 pathway in KYSE450 tumor bearing mice was investigated." (PMID 32733803, 2020).
esophageal squamous cell carcinoma (6 papers, 2020 to 2025). Esophageal squamous cell carcinoma (ESCC) is a type of esophageal carcinoma (EC) that can affect any part of the esophagus, but is usually located in the upper or middle third.
osteoporosis (6 papers, 2022 to 2025). A condition of reduced bone mass, with decreased cortical thickness and a decrease in the number and size of the trabeculae of cancellous bone (but normal chemical composition), resulting in increased fracture incidence. "The aim of this study was to investigate the potential of hsa_circ_0004276 as a diagnostic marker for Postmenopausal Osteoporosis (PMO) and its potential interaction with the RNA-binding protein ELAV-like RNA binding protein-1 (ELAVL1)." (PMID 40803272, 2025). "Recent research indicates that ELAV-like RNA binding protein 1 (ELAVL1) inhibits the translation of SIRT1, disrupts osteoblast differentiation mediated by ferroptosis, and thereby impedes the progression of osteoporosis." (PMID 41551515, 2025).
sarcoma (6 papers, 2018 to 2024). A usually aggressive malignant neoplasm of the soft tissue or bone. "Here, we report the identification of the RNA-binding protein HuR/ELAVL1 as a central oncogenic driver for malignant peripheral nerve sheath tumors (MPNSTs), which are highly aggressive sarcomas that originate from cells of the Schwann cell lineage." (PMID 32315290, 2020). "Additionally, runt-related transcription factor 1 (RUNX1) negatively regulates circPTPN22 expression, while RNA-binding proteins such as FUS (fused in sarcoma) and ELAVL1 (recombinant ELAV-like protein 1) positively regulate its expression." (PMID 38956466, 2024). "Importantly, we identified the runt-related transcription factor 1 (RUNX1) and RNA-binding proteins (RBPs) fused in sarcoma (FUS) protein and recombinant ELAV-like protein 1 (ELAVL1) as mediators of circPTPN22 biogenesis." (PMID 38956466, 2024).
autism (5 papers, 2016 to 2022). Persistent deficits in social interaction and communication and interaction as well as a markedly restricted repertoire of activity and interest as well as repetitive patterns of behavior. "In addition, for some of these novel genes (e.g., CALM1 and ELAVL1), although no available study has demonstrated their connection with schizophrenia or nicotine addiction directly, they have been identified as risk factors for other mental disorders including autism and drug addictions." (PMID 29440730, 2018).
colitis (5 papers, 2018 to 2025). Inflammation of the colon. "Studies support a single m6A regulator participating in the immune-associated colitis-like methyltransferase 14 (METTL14) deletion in T-cells trigger spontaneous colitis, and m6A reader ELAV-like RNA binding protein 1 (ELAVL1, also known as HuR) maintain colonic epithelial Paneth cells’ function." (PMID 35127705, 2021).
leukemia (5 papers, 2014 to 2025). A malignant (clonal) hematologic disorder, involving hematopoietic stem cells and characterized by the presence of primitive or atypical myeloid or lymphoid cells in the bone marrow and the blood. "ELAVL1/HuR is reported to be dysregulated in leukaemia, lymphoma and a range of other cancer types, generally showing overexpression." (PMID 38329136, 2024). "Moreover, GSPT1 interacted with ELAVL1 and EIF4B, proteins associated with favorable AML outcomes, while KPNA1 negatively interacted with PPP1CA, a marker of poor prognosis, suggesting its role in modulating negative prognostic pathways in leukemia." (PMID 39940906, 2025).
myocardial ischemia (5 papers, 2021 to 2025). A disorder of cardiac function caused by insufficient blood flow to the muscle tissue of the heart. "For example, ELAVL1 was activated by FOXC1 to promote cardiomyocyte ferroptosis during myocardial ischemia‐reperfusion injury." (PMID 40401147, 2025). "Therefore, this study aimed to investigate the functional roles and mechanisms by which ELAVL1 regulates myocardial ischemia and reperfusion (I/R) injury." (PMID 33568052, 2021). "For example, ELAVL1 could promote ferroptosis by regulating autophagy in myocardial ischemia/reperfusion injury." (PMID 34440579, 2021). "Targeting ferroptosis or FOXC1/ ELAVL1 could be beneficial for myocardial ischemia patients." (PMID 33568052, 2021).
nasopharyngeal carcinoma (5 papers, 2020 to 2024). A carcinoma arising from the nasopharyngeal epithelium. "In conclusion, our study has confirmed the association of ELAVL1 with aerobic glycolysis in nasopharyngeal carcinoma cells." (PMID 39390359, 2024). "Our study provides additional evidence for the involvement of ELAVL1 in promoting the proliferation and progression of nasopharyngeal carcinoma." (PMID 39390359, 2024). "Regarding ELAVL1, its impact on other glucose metabolism pathways in nasopharyngeal carcinoma requires further investigation." (PMID 39390359, 2024). "Our research aims to investigate how ELAVL1 controls the glycolytic process in nasopharyngeal carcinoma cells through the HMGB3/β-catenin pathway." (PMID 39390359, 2024). "In this study, we determined the regulatory role of ELAVL1 in the glycolytic process of nasopharyngeal carcinoma cells via the HMGB3/β-catenin axis." (PMID 39390359, 2024). "The expression of ELAVL1 was detected in clinical tumor samples and nasopharyngeal carcinoma cell lines." (PMID 39390359, 2024). "In both clinical samples and nasopharyngeal carcinoma cell lines, the expression levels of ELAVL1 mRNA and protein were found to be upregulated." (PMID 39390359, 2024). "Knockdown of ELAVL1 significantly inhibited the in vivo proliferation of nasopharyngeal carcinoma and suppressed the glycolytic capacity of nasopharyngeal carcinoma cells." (PMID 39390359, 2024). "Our research provides novel insights into the tumor metabolism and growth mechanisms of nasopharyngeal carcinoma, and identifies ELAVL1 as a promising potential therapeutic target for this disease." (PMID 39390359, 2024). "To further validate this finding, we conducted qRT-PCR analysis to compare the mRNA expression levels of ELAVL1 in nasopharyngeal carcinoma tissues and normal tissues." (PMID 39390359, 2024). "These discoveries offer mechanistic insights into the involvement of ELAVL1 in the glycolysis of nasopharyngeal carcinoma and suggest potential therapeutic targets for this disease." (PMID 39390359, 2024). "Compared to normal tissues, the level of ELAVL1 protein is elevated in various types of cancer, including nasopharyngeal carcinoma, breast cancer, prostate cancer, and pancreatic cancer." (PMID 39390359, 2024). "Our study found that transfection of sh-ELAVL1 into nasopharyngeal carcinoma cell lines led to a substantial decrease in glucose consumption and lactate production." (PMID 39390359, 2024). "Collectively, these findings suggest a role for ELAVL1 in promoting glycolysis in nasopharyngeal carcinoma cells." (PMID 39390359, 2024). "ELAVL1 promotes glycolysis in nasopharyngeal carcinoma cells by interacting with HMGB3 to stabilize HMGB3 mRNA, thereby activating β-catenin pathway." (PMID 39390359, 2024). "LncRNA SNHG7 promotes the proliferation and migration of nasopharyngeal carcinoma by miR-514a-5p/ ELAVL1 axis." (PMID 32370736, 2020). "Therefore, ELAVL1 can activate the downstream Wnt/β-catenin signaling, either directly or indirectly, in nasopharyngeal carcinoma." (PMID 39390359, 2024). "HMGB3 is involved in ELAVL1-mediated glycolysis in nasopharyngeal carcinoma cells." (PMID 39390359, 2024). "In addition, our experiments revealed that the suppressive impact of sh-ELAVL1 on the glycolytic ability of nasopharyngeal carcinoma cells was reversed upon subsequent overexpression of HMGB3." (PMID 39390359, 2024). "Additionally, we focused solely on evaluating the impact of ELAVL1 on the glycolysis of nasopharyngeal carcinoma cells." (PMID 39390359, 2024). "ELAVL1 promotes glycolysis in nasopharyngeal carcinoma cells." (PMID 39390359, 2024). "Due to limitations in the experimental design, we were unable to clarify whether the translocation of ELAVL1 exists in nasopharyngeal carcinoma cells." (PMID 39390359, 2024).
nasopharyngeal carcinoma (continued). "Furthermore, another research uncovered that individuals with elevated ELAVL1 expression had shorter overall survival and progression-free survival compared to those with low ELAVL1 expression, supporting the clinical relevance of ELAVL1 in nasopharyngeal carcinoma prognosis." (PMID 39390359, 2024). "However, the role of ELAVL1 in glycolysis in nasopharyngeal carcinoma remains largely unknown." (PMID 39390359, 2024). "These discoveries lead us to propose a hypothesis that ELAVL1 interacts with HMGB3 to enhance its stability, thereby promoting aerobic glycolysis in nasopharyngeal carcinoma cells by further activating the β-catenin pathway." (PMID 39390359, 2024). "Initially, through data mining of clinical databases and testing in cell lines, we discovered a substantial upregulation of ELAVL1 expression in nasopharyngeal carcinoma cells compared to normal cells." (PMID 39390359, 2024).
non-alcoholic fatty liver disease (5 papers, 2021 to 2025). "ELAVL1 also protects against non-alcoholic fatty liver disease (NAFLD), a condition that associates with increased risk of coronary artery calcification." (PMID 34760935, 2021).
Sepsis (5 papers, 2015 to 2025). Sepsis is defined as life-threatening organ dysfunction caused by a dysregulated host response to infection. "Another top gene identified in this study was ELAVL1, which encodes HuR protein, playing a critical role in post-transcriptional regulation, splicing and suppression of thrombomodulin synthesis in interleukin-1β (IL-1β) treatment and sepsis." (PMID 35938548, 2022).
Alzheimer disease (4 papers, 2015 to 2024). A progressive, neurodegenerative disease characterized by loss of function and death of nerve cells in several areas of the brain leading to loss of cognitive function such as memory and language. "The single-gene enrichment analysis of ELAVL1 in MDD patients in this study showed enrichment in pathways such as Alzheimer’s disease, neurodegenerative disease pathways, Parkinson’s disease, and cellular senescence." (PMID 38714976, 2024).
autoimmune (4 papers, 2009 to 2024). "Furthermore, we show that this transition plays an important role in the persistence of activated T cells, suggesting that the upregulation of Elavl1 in the endothelium is an important contributor to the breakdown of local barriers to autoimmunity observed in atherosclerotic lesions." (PMID 39131295, 2024).
glaucoma (4 papers, 2018 to 2025). Increased pressure in the eyeball due to obstruction of the outflow of aqueous humor. "Reduced cytoplasmic Elavl1 in glaucoma models and human samples leads to lower levels of these proteins, contributing to glaucoma development." (PMID 40000387, 2025). "ELAVL1 has already been proven to be involved in glaucoma pathogenesis." (PMID 39458974, 2024).
acute respiratory distress syndrome (3 papers, 2017 to 2021). Progressive and life-threatening pulmonary distress in the absence of an underlying pulmonary condition, usually following major trauma or surgery. "ELAVL-1 is known to promote proinflammatory factors in fibroblasts, T cells and macrophages, and has also been implicated to play a role in promoting acute respiratory distress syndrome, although the exact mechanism is still not known." (PMID 33478018, 2021).
chronic obstructive pulmonary disease (3 papers, 2016 to 2022). A chronic and progressive lung disorder characterized by the loss of elasticity of the bronchial tree and the air sacs, destruction of the air sacs wall, thickening of the bronchial wall, and mucous accumulation in the bronchial tree. "Additionally, a recent study showed that there is a significant positive correlation between ELAVL1 and ACE2 in chronic obstructive pulmonary disease (COPD) cells." (PMID 35938548, 2022).
endometrial carcinoma (3 papers, 2024 to 2025). A malignant tumor arising from the epithelium that lines the cavity of the uterine body. "RT-qPCR and Western blotting results similarly demonstrated a significant enhancement of ELAVL1 expression in endometrial cancer cell lines (HEC-1A, Ishikawa, RL95–2, HEC-1B, and AN3CA) compared to ESC cells (p < .05)." (PMID 40018990, 2025). "In our study, we discovered that ELAVL1 plays a significant role in regulating the malignant behavior of endometrial cancer cells through the modulation of LncRNA NEAT1-mediated regulation of Beclin1 expression." (PMID 40018990, 2025). "In summary, our study showed that ELAVL1 regulated the malignant behavior of endometrial cancer cells through the modulation of LncRNA NEAT1-mediated regulation of Beclin1 expression." (PMID 40018990, 2025). "ELAVL1, an RNA-binding protein, plays a significant role in various cancers, including endometrial carcinoma." (PMID 38981872, 2024). "This complex interaction between ELAVL1, RNA molecules, and miRNAs contributes to the progression and characteristics of endometrial carcinoma." (PMID 38981872, 2024). "Our study has elucidated a crucial pathway in the pathogenesis of endometrial cancer (EC) involving the interaction between ELAVL1 and HOTAIR, which in turn influences the regulation of SOX17." (PMID 38981872, 2024). "This indicated that high ELAVL1 expression in endometrial cancer might facilitate cancer progression through its regulation of Beclin1." (PMID 40018990, 2025). "Our study aims to investigate the roles of embryonic lethal abnormal vision-like 1 (ELAVL1) and long non-coding RNA (LncRNA) NEAT1 in endometrial cancer (EC), focusing on their underlying molecular mechanisms.We obtained EC cell lines (HEC-1A, Ishikawa, RL95–2, HEC-1B, and AN3CA) from ATCC." (PMID 40018990, 2025). "We first queried the TCGA database for the expression of ELAVL1 in endometrial cancer." (PMID 40018990, 2025). "Based on our comprehensive analysis, we propose the following hypothesis: The transcription factor ZBTB7A suppresses the expression of ELAVL1 by transcriptionally inhibiting LncRNA HOTAIR, which in turn inhibits the malignant biological behavior and angiogenesis in endometrial carcinoma." (PMID 38981872, 2024).
epilepsy (3 papers, 2016 to 2018). A brain disorder characterized by episodes of abnormally increased neuronal discharge resulting in transient episodes of sensory or motor neurological dysfunction, or psychic dysfunction. "Several genes which have been linked to cell death in cancer, epilepsy, or psychological disorders but not yet associated with brain injury, including CSNK2A1, ELAVL1, MITF, and SMARCA4, were also identified which may provide additional therapeutic targets for prevention of cell death following TBI." (PMID 26912237, 2016).
multiple myeloma (3 papers, 2021 to 2025). "Specifically, lncRNA HOXB-AS1 has been testified to recruit ELAVL1 and thereby maintain FUT4 mRNA stability in multiple myeloma." (PMID 34911544, 2021).
ovarian tumors (3 papers, 2016 to 2021). "Human antigen R (HuR, ELAVL1) is an expressed RNA-binding protein that is very highly expressed in different ovarian tumors." (PMID 34641519, 2021).
periodontitis (3 papers, 2021 to 2022). An acute or chronic inflammatory process that affects the tissues that surround and support the teeth. "This indicated ELAVL1 andCBLL1 played an important role in TNF or cytokine reactions in periodontitis." (PMID 33724691, 2021).